PSG6 (pregnancy specific beta-1-glycoprotein 6)
Synonyms: PSBG-6; PSBG-10; PSBG-12; PSG10; PSGGB
Tractability: Antibody: UniProt places it where antibodies can reach, with high confidence; UniProt predicts a signal peptide or a membrane-spanning region; its Gene Ontology location is reachable by antibodies, with medium confidence.
Gene: Protein-coding gene on chromosome 19 (42,902,086 to 42,919,563, reverse strand). Ensembl gene ENSG00000170848.
Subcellular location: Secreted
Pathways (Reactome):
Hemostasis: Cell surface interactions at the vascular wall
Gene Ontology:
Biological process: female pregnancy
Cellular component: extracellular region
Genetic constraint (gnomAD): Loss-of-function variants: 51 observed, 43.4 expected, observed/expected ratio (o/e) 1.17, 90% interval 0.94 to 1.48. The synonymous counts are far from expectation, so gnomAD's model fits this gene poorly and the ratio says little. Missense variants: 770 observed, 527.83 expected, observed/expected ratio (o/e) 1.46, 90% interval 1.37 to 1.55. Synonymous variants: 292 observed, 199.5 expected, observed/expected ratio (o/e) 1.46, 90% interval 1.33 to 1.61.
Homologues: Paralogues in human: PSG3 (88% identical), PSG9 (88% identical), PSG7 (88% identical), PSG4 (88% identical), PSG8 (87% identical), PSG1 (86% identical), PSG5 (67% identical), PSG11 (65% identical), PSG2 (65% identical), CEACAM1 (41% identical), CEACAM5 (38% identical), CEACAM6 (36% identical), and 12 more.
Diseases named in the same sentence as PSG6 in open-access papers:
PSG6 is named in the same sentence as 3 diseases in open-access papers, as found by Europe PMC text mining. Sharing a sentence is not in itself a finding about the gene and the disease. The quoted sentences say what the papers report.
gestational hypertension (2 papers, 2014 to 2019). "PSG6 have been recently found to be located within a genomic region enriched in segmental duplication of preeclampsia patients." (PMID 30917529, 2019).
tumour (1 paper, 2026). "PSG6 also showed selective anticancer effects, reducing tumour cell viability at micromolar concentrations, inducing mitochondrial fission, and lowering the mitochondrial membrane potential (ΔΨm) at 10 μM." (PMID 42134299, 2026).
PSG6 also shares sentences with these, for which no sentence is quoted: stomach adenocarcinoma (1 paper).